NOS2 (nitric oxide synthase 2)
Diseases named in the same sentence as NOS2 in open-access papers (continued):
Sharing a sentence is not in itself a finding about the gene and the disease.
glioma (continued). "As observed in the U-87 MG and T98G cell lines, glioma primary cells cultured in St-M basically expressed NOS2." (PMID 30227679, 2018). "In a recent study, our group reported that NOS2 expression was highly and significantly upregulated in glioma cells that were kept in the specific medium for neurosphere generation." (PMID 30227679, 2018). "NOS2, which is basically expressed in the U-87 MG, T98G glioma cell lines and human glioma primary cells, was confirmed to be upmodulated in the relative neurospheres generated in specific culture conditions." (PMID 30227679, 2018). "Our group has recently shown that the basal levels of NOS2/NO system expression significantly increased in the glioma cell derived-neurospheres." (PMID 30227679, 2018). "Elevated NO synthase 2 (NOS2) expression correlates with decreased survival in human glioma patients." (PMID 28157712, 2017). "Previously, we and others have demonstrated that NOS2 inhibition slowed colon and glioma stem cells growth in vivo animal models." (PMID 28157712, 2017). "The rat G1A1 glioma cell line used in this study expressed Nos2 and low levels of the other Nos. While Nos2 expression was highly variable in vitro, it was over-expressed and stable in the xenografts." (PMID 25768009, 2015). "In contrast, Nos2 expression in cultured glioma cells depended on the cell density and was very variable (not shown)." (PMID 25768009, 2015). "In rat C6 glioma cells, NOS2 induction by over-expression of MAPKs was blocked by a dominant negative form of C/EBPβ." (PMID 19323834, 2009). "Sixty glioma-associated targets were associated with CHR, such as MDR transporters (ABCB1, ABCC1, ABCG2), cyclin-dependent kinases (CDK1, CDK6), matrix metalloproteinases (MMP2, MMP9, MMP12), and genes related to inflammation or oxidative stress (NOS2, NOX4)." (PMID 40963691, 2025). "Moreover, Mn enhances lipopolysaccharide (LPS)-induced inflammatory response, NOS2 expression, and mitochondrial ROS production in glioma C6." (PMID 38132161, 2023). "Interestingly, the gene expression of markers connected to a pro-inflammatory response, Il1b and Nos2, were also detected at high levels in glioma-infiltrating cells." (PMID 32555306, 2020). "Of note, 1400W, at an effective concentration to inhibit NO generation, was able to significantly reduce the proliferation, migration, colony formation, and neurosphere generation abilities of glioma cells, thus supporting the emerging relevance of NOS2 as a functional player in glioma biology." (PMID 30227679, 2018). "Similarly, also, glioma primary cell-derived neurospheres showed higher levels of NOS2 expression and activity when compared to the adherent tumor cells cultured in standard conditions." (PMID 30227679, 2018). "Importantly, glioma stem cell activity depends on NOS2 activity for tumor growth and tumorigenicity, as evaluated after xenotransplantation in NOD/SCID mice." (PMID 30279357, 2018). "Thus, the NOS2/NO system as a biomarker for glioma and/or as a potential pharmacological target is extremely promising." (PMID 30227679, 2018). "Importantly, pharmacological NOS2 inhibition slows glioma growth in a murine intracranial glioma model." (PMID 30279357, 2018). "The involvement of NOS2 activity was also investigated in the human glioma primary cells." (PMID 30227679, 2018). "Glioma cells are also dependent on NOS2 (nitric oxide synthase-2) activity for tumour growth." (PMID 29099032, 2017). "Furthermore, we demonstrated by qRT-PCR that the transplanted glioma cells highly expressed Nos2, Vegfa and Cyclin D1 mRNA." (PMID 25768009, 2015). "Nos2 was clearly overexpressed in the xenografted glioma cells when compared to Nos1 and Nos3." (PMID 25768009, 2015). "This could be explained by cellular heterogeneity in this mixed rat glioma line or shear stress that has been reported to able to induce NOS2 expression." (PMID 25768009, 2015).
glioma (continued). "We propose that the NO/Ets-1 signaling axis first described here may promote disease progression in other tumors that overexpress NOS2, such as glioma and melanoma, and tumors with impaired SNO metabolism, such as lung and hepatocellular carcinoma." (PMID 22971289, 2012). "We detected genes upregulated in PBT030 cells, such as SOX2, MYCN, NOS2, RUNX2, and VEGFA, while PBT147 cells upregulated level of PTEN, STAT6, CA9 and TLR2, demonstrating differences among PBT cell lines, which can be explained by various driving mutations and heterogeneity in glioma lines." (PMID 38449858, 2024). "A further network pharmacological analysis showed that NOS2 was indeed a great, promising target for formononetin and calycosin (FMN/CAL) to regulate metabolism in temozolomide-treated C6 glioma cells." (PMID 37298670, 2023). "We analyzed the effect of NOS2 inhibitor 1400W on the autophagic flux and extracellular vesicle (EV) secretion in U87MG glioma cells." (PMID 31226744, 2019). "In addition, based on metabolomics and molecular biology studies, nitric oxide synthase 2 (NOS2) was a key target for FMN and calycosin to regulate TMZ in the treatment of glioma." (PMID 40098623, 2025). "Nos2 is known to promote drug resistance in lung cancer by activation of the canonical Wnt pathway through inhibition of DKK1 and to promote the growth of CSCs in glioma via the Notch pathway." (PMID 31796785, 2019). "In fact, it was shown that glioma stem cells produce NO via elevated nitric oxide synthase-2 (NOS2) activity and this property is not observed in normal neural progenitor cells or in their less tumorigenic (i.e., CD133− cells) counterpart." (PMID 30279357, 2018). "NOS2 knockdown by RNA interference strategy or by specific inhibitors negatively affected the proliferation and invasiveness of GBM cells, and was able to reduce the progression of subcutaneous and intracranial human glioma xenografts in mice." (PMID 30227679, 2018). "Of note, we recently and firstly showed a high and significant correlation between NOS2 and SOX-2 expression in glioma cells.Collectively, all of these studies, among others, suggest that NO signaling plays an important role in GSC maintenance and resistance to anticancer therapies." (PMID 30227679, 2018). "Moreover, a high and significant correlation was observed among the expression of NOS2 and SOX-2 (Sex determining region Y-box 2), which is a stemness marker that is aberrantly upregulated in both human glioma cell lines and primary cultures." (PMID 30227679, 2018). "NOS2 and VAV3 stimulate glioma-initiating cell proliferation and tumour growth in xenograft models." (PMID 29152145, 2017). "NOS2, also called inducible NOS (iNOS), is highly expressed in glioma CSCs (GSCs)." (PMID 28009990, 2017).
Obesity (31 papers, 2013 to 2025). Accumulation of substantial excess body fat. "The macrophage infiltration (% CD11b+F4/80+ of viable cells) was similar between tumors from lean and obese mice, but obesity was associated with an increased proportion of mixed M1-M2-type (% CD206+NOS2+ of CD11b+F4/80+ cells)." (PMID 35720277, 2022). "Obesity is associated with increased Nos2 expression in insulin-sensitive tissue in rodents and humans." (PMID 32961723, 2020). "NO∙ is synthesized at high rates by the inducible form of nitric oxide synthase (iNOS, encoded by the NOS-2 gene) which plays a significant role in cell damage associated with obesity and T2DM." (PMID 25814786, 2015). "By contrast, obesity induced increasing gene expression of molecules characteristic of M1 macrophages, such as those encoding TNF and NOS2, suggesting that diet-induced obesity leads to a change from M2 to M1 polarization." (PMID 26074923, 2015). "Our results contribute to a deeper understanding of the critical roles of NOS2 in obesity-induced MHD." (PMID 41077251, 2025). "Overall, the reduction of hepatic Ucp2 and Nos2 expression in DIO mice treated with PGG indicated a preventive effect on obesity but also on non-alcoholic steatohepatitis." (PMID 35409415, 2022). "The NOS2 rs2297518 [A/G] and NOS3 rs1799983 [G/T] genetic variations were associated with insulin resistance, obesity, and/or a higher BMI in several populations." (PMID 33924357, 2021). "The results of these studies show that inhibiting NOS2 or blocking the action of NO on afferent pathways can be used to treat obesity." (PMID 33374571, 2020). "We particularly demonstrate that obesity impairs hepatic PGC-1α up-regulation and, thus, enhances Nos2 transcriptional expression and causes nitrosative stress in the liver during AP." (PMID 32961723, 2020). "A few years later, intensive work began on the inhibition of NOS2 that would contribute to the treatment of obesity." (PMID 33374571, 2020). "In contrast, IL1B and NOS2 were significantly increased in islets from obese, compared to non-obese individuals, implying a more inflammatory macrophage phenotype in islets in obesity." (PMID 31787760, 2019). "On the basis of this empirical observation, we propose the -51T→C substitution in the NOS2 gene promoter as a candidate SNP marker of obesity." (PMID 26694100, 2015). "In the state of obesity, macrophages are polarised into pro-inflammatory M1, nitric oxide synthase 2 (NOS2) is activated, and reactive oxygen species such as NO, CD11c are produced, as well as tumor necrosis factor alpha (TNF-α), IL-6, IL-1β, IL-12, and monocyte chemotactic protein are secreted." (PMID 41301704, 2025). "Furthermore, after high-fat diet (HFD) feeding, knockout of NOS2 in rat MSCs resulted in significant obesity." (PMID 33816486, 2021). "WT and NOS2–/– rats were fed a NCD or a HFD for 8 weeks to induce obesity." (PMID 33816486, 2021). "This study shows that blocking CB1 receptors and NOS2 may be of great therapeutic importance in alleviating obesity-related CKD." (PMID 33374571, 2020). "Nitric oxide 2 (NOS2), called “iNOS,” is also involved in obesity-related lysosomal dysfunction." (PMID 31357643, 2019). "The authors also reported that obesity promotes NOS2 localization to lysosomes and results in accumulated lysosomal NO in the liver and that the overproduction of lysosomal NO exacerbates lysosomal nitrosative stress with impairment of lysosomal function and autophagy." (PMID 31357643, 2019). "Diet-induced obesity did not alter expression of Tnfa, Nos2, Il12, Il10, but was associated with a significant increase in Retnla expression and a small reduction in Il6, and Arg1 expression." (PMID 26956558, 2016). "In this work, an additional keyword search (hereinafter) pointed to new data suggesting that NOS2 overexpression may be a biochemical marker of obesity." (PMID 26694100, 2015). "Also both in obesity and in diabetes, an increase in the expression of NOS-2 and of COX-2 has been reported." (PMID 25610861, 2014).
Obesity (continued). "As an early model to assess obesity associated HFpEF development, mice on WD had no significant increase in nitrosative stress or cardiac fibrosis, two players in the pathogenesis of HFpEF, indicated by no changes in nos2 and col1a2 expression levels." (PMID 36844730, 2023). "However, neither M2-type-(CD206+NOS2-) nor M1-type-(CD206+NOS2-) tumor associated macrophages were altered by obesity." (PMID 35720277, 2022). "Despite advances in understanding EAT and key inflammatory mediators such as NOS2 in obesity-induced MHD, critical gaps remain, such as clarifying specific cell types responsible for NOS2 effects." (PMID 41077251, 2025).
diabetes (29 papers, 2009 to 2025). "NO derived from NOS2 most often causes β-cell dysfunction, impaired insulin secretion, hyperglycemia and the development of diabetes." (PMID 33374571, 2020). "For example, the NOS2 rs2297518 variant showed a significant correlation with diabetes mellitus." (PMID 33924357, 2021). "NOS2 expression is dramatically increased in diabetic mice, and evidence suggests that excess NOS2 contributes to diabetes-induced heart defects by increasing nitrosative stress and cell apoptosis." (PMID 36672920, 2023). "Serum LDL-C levels also showed weak positive correlation with SOD2 (r = 0.113, p = 0.047), and type 2 diabetes mellitus showed moderate correlation with NOS2 (r = 0.397, p < 0.001)." (PMID 33924357, 2021). "Berberine reduces proteinuria and kidney damage caused by diabetes and hypertension through two key targets, PTGS2 and NOS2, which improve podocyte injury." (PMID 32025234, 2020). "Our data revealed that CoPP treatment blocked the increased expression of CD11b/c and NOS2 induced by diabetes (p<0.017; one-way ANOVA versus STZ vehicle treated mice)." (PMID 26730587, 2016). "In terms of decreasing oxidative stress, aminoguanidine, an oral insulin stimulant for type 2 diabetes mellitus and a specific inhibitor of inducible nitric oxide synthase (NOS-2), was experimentally shown to prevent the development of GON." (PMID 27433524, 2014). "NOS2 plays an important role in neurovascular degeneration in retinopathies including those mediated by acute ischemia and diabetes." (PMID 19626134, 2009). "However, 6 months after the induction of diabetes, the expression levels of Ccl2, Il1b, Il6, Tnf, Tgfb and Inos (Nos2) were significantly higher in the Il33−/− retina than in the WT retina." (PMID 37671525, 2023). "Many reports have shown that diabetes results in proinflammatory, phagocytic microglial activation, characterized by an ameboid shape with truncated, retracted cellular processes and microglia-derived IL-1β and NOS2 production." (PMID 36517889, 2022). "Moreover, pharmacological blockade of p300/CBP significantly reduced the diabetes-associated inflammatory response in the kidney, as demonstrated by the knock-down effects on MCP-1, TNFα, NOS2, ICAM-1, VCAM-1, and E-selectin transcript levels." (PMID 34572988, 2021). "In diabetes mellitus (DM), particularly T2DM, miR-185 expression is often reduced, coinciding with upregulation of NOS2, suggesting a role in inflammatory pathways." (PMID 40282289, 2025). "Inhibition of ZIPK also decreases NOS2 expression and oxidative stressin vivo, suggesting that ZIPK has therapeutic potential for diabetic vascular complications." (PMID 39030705, 2024). "Our results show that neither diabetes nor homoarginine affected NOS1 or NOS2 gene expression in NOS3−/− mice." (PMID 33713581, 2021). "Finally, gene expression of NOS2 was not significantly affected by diabetes in both WT and AT2R−/y mice." (PMID 28361992, 2017).
atherosclerosis (28 papers, 2013 to 2025). A disease characterized by the build-up of fatty material and calcium deposition in the arterial wall resulting in partial or complete occlusion of the arterial lumen. "The upregulation of NOS2 expression in inflammatory states is related to the presence of pathogen molecules or cytokines that are highly associated with atherosclerosis." (PMID 31434316, 2019). "In contrast to this, in a state of established atherosclerosis (atherosclerotic plaques), miR-342-5p has been described to induce pro-inflammatory mediators including nitric oxide synthase 2 (Nos2) and IL-6." (PMID 33003647, 2020). "It has been demonstrated in various vascular disease states (including atherosclerosis and restenosis) that NOS2 expression is upregulated in vascular SMC including those cells found in the neointima." (PMID 27402344, 2016). "An inducible isoform of NOS (iNOS; Nos2) is expressed in vascular smooth muscle, endothelium, and myocardium in certain pathological conditions such as atherosclerosis, diabetes, and inflammatory disorders." (PMID 25226386, 2014). "In aging or diseases such as inflammation, hypertension, and atherosclerosis, O2•− formation increases dramatically and at the same time inducible NO synthase (NOS2) generates high concentrations of •NO." (PMID 23567270, 2013). "NOS2, also known as inducible Nitric Oxide Synthase (iNOS), is a key enzyme synthesizing nitric oxide (NO) under specific inflammatory conditions, including atherosclerosis." (PMID 36937936, 2023). "The induction of NOS2 by P2C7 peptide is also very relevant in the context of atherosclerosis." (PMID 31434316, 2019). "While, we observed an obvious downregulation of pro-inflammatory markers (Il1b, Tnfa, Nos2) after Kdm2a knockdown after ox-LDL stimulation, which revealed the specific role of KDM2A in macrophages during atherosclerosis." (PMID 40303308, 2025). "Our finding that GBH contains five core compounds (quercetin, kaempferol, baicalein, ellagic acid, and baicalin) that can be linked to six potential target genes (AKT1, CASP3, MAPK1, MAPK3, NOS2, and PTGS2) related to atherosclerosis is in agreement with previous reports." (PMID 33321972, 2020).